RNF2 (ring finger protein 2)
Diseases named in the same sentence as RNF2 in open-access papers (continued):
Sharing a sentence is not in itself a finding about the gene and the disease.
tumor (continued). "Results show that the RNF2 knockdown tumor tissue had decreased PCNA level while increased cleaved caspase-3 level than the control tissues." (PMID 28029659, 2017). "The RNF2 expression level was also analyzed with PCa tumor grade, and results showed that the RNF2 expression was significantly higher in high grade PCa(Gleason>7) (H-Score: 150.5±62.03) than low grade PCa(Gleason≤7) (H-Score: 97.10±53.63)." (PMID 28029659, 2017). "In selective tumor types, RNF2 can promote tumor development through poly ubiquitinates tumor suppressor TP5315." (PMID 26869491, 2016). "A recent study reported that RNF2 was overexpressed in ductal breast carcinoma cells and involved in tumor progression." (PMID 26869491, 2016). "To investigate the relationships between RRM1, RNF2, and Bmi1 in human tumor samples from patients with NSCLC, we used a tissue microarray consisting of 3 replicates of 187 surgically resected patients with stage I disease." (PMID 24614341, 2014). "Furthermore, RT-qPCR analysis did not reveal a significant upregulation of Ring Finger Protein 2 (RNF2) in the tumor group, with a p-value of 0.1686, which was above the threshold for statistical significance." (PMID 40809844, 2025). "Our data showed that RNF2 silencing slowed tumor growth and reduced tumor weight in vivo." (PMID 36271315, 2023). "Since these clinical characteristics were closely related to tumor metastasis, we suspected that high expression RNF2 might contribute to HCC metastasis and result in poor prognosis." (PMID 37037816, 2023). "Moreover, univariate Cox analysis identified AFP level (p = 0.012), number of tumor (p < 0.001), MVI (p < 0.001), TNM stage (p < 0.001) and RNF2 expression (p = 0.002) to be risk factors for HCC patients." (PMID 37037816, 2023). "Similarly, in our own cohort composed of 83 HCC specimens, the protein level of RNF2 was significantly elevated in HCC tumor, and its expression was increased in high immunoreactivity score (IRS) group." (PMID 37037816, 2023). "High RNF2 expression was detected in tissues of ESCC patients and linked to increased tumor volume." (PMID 35129056, 2022). "Hypermethylated promoter regions in ALK tumor cells showed strong enrichment of binding sites for proteins associated with chromatin remodeling in ESC, in particular PRC associated proteins including CBX7, EZH2, MTF2, PHF19, RING1B, RNF2, and SUZ12." (PMID 33310759, 2021). "RNF2 is a transcription factor, which has been reported to be related to the tumor progression." (PMID 34235075, 2021). "However, only DUXAP8 and RNF2 showed prognostic value in multivariate analysis, after adjustment for tumor stage, HBV infection, and radical resection factors (adjusted p=0.014 and 0.008, respectively)." (PMID 32922554, 2020). "To evaluate whether knockdown of RNF2 can inhibit PCa tumor growth in vivo, we knocked down RNF2 expression using shRNA expressing lentivirus in DU145 cells." (PMID 28029659, 2017). "In this study, we found that PCa tissues have much higher RNF2 expression than BPH tissues, and RNF2 expression is positively correlated with tumor grade, indicating that RNF2 may have oncogenic function in PCa." (PMID 28029659, 2017). "Results show that the tumor growth in RNF2 knockdown group (shRNF2 #1 and shRNF2 #2) was dramatically inhibited compared with the control (shScr) group, with the final tumor volume of 304.33±63.72 mm3, 331.93±84.42 mm3 and 846.80±55.29 mm3, respectively (p<0.05)." (PMID 28029659, 2017). "In addition, RNF2 knockdown DU145 xenografts showed significantly inhibited tumor growth in nude mice." (PMID 28029659, 2017). "On the contrary, our findings confirmed that restoration of SIK1 induced by RNF2 depletion could inhibit cell growth and induce cell apoptosis in HCC cells, and that SIK1 siRNA can counteract the inhibitory effect of RNF2 lost on tumor growth." (PMID 27911266, 2017).
tumor (continued). "Because of the high RNF2 level in PCa tumor tissues and the inhibited cell proliferation and increased apoptosis in RNF2 knockdown cells, we conclude that RNF2 may be used as a new biomarker for diagnosis and new target for the therapy of PCa." (PMID 28029659, 2017). "We next examined the effect of the abnormal expression of RNF2 on tumor metastasis in vivo." (PMID 27911266, 2017). "The role of MMP1 in modulating the tumor microenvironment (TME) has been well documented, and RNF2, which functions as an E3 ubiquitin ligase, plays a crucial role in regulating cell-cycle progression and the DNA damage response." (PMID 40809844, 2025). "High expression of RNF2 was positively correlated with microvascular invasion (MVI) (p = 0.019), number of tumor (p = 0.010) and advanced TNM stage (p = 0.039)." (PMID 37037816, 2023). "The mechanism of miR-539-3p-mediated tumorigenesis was targeted SPARCL1, RNF2, CTBP1, or CDK14 and inhibited the expression of these proteins in tumor cells." (PMID 35303885, 2022). "Using GO biological process enrichment analysis, we found that CUL1, CUL3, RNF2, and RPA2 overlap in their mitotic cell cycles, which has important biological implications in tumor development." (PMID 32170141, 2020). "A nomogram was constructed using tumor stage, HBV infection status, radical resection status, and expressions of DUXAP8 and RNF2." (PMID 32922554, 2020). "To further investigate the expression patterns of RNF2 and SIK1 in HCC, we randomly examined six pairs of human HCC samples and matched non-tumor tissues." (PMID 27911266, 2017). "The down-regulation of RNF2 expression in HCC cells significantly reduces tumor cell growth and metastasis, while the simultaneous down-regulation of both RNF2 and SIK1 restores tumor cell growth in vitro and in tumor xenograft models." (PMID 27911266, 2017). "RING Finger Protein 2 (RNF2), an E3 ubiquitin ligase, mediates monoubiquitination of histone H2A at lysine 119 (H2AK119ub), resulting in chromatin compaction and transcriptional silencing of tumor suppressor genes." (PMID 41199817, 2025). "Low expressions of DUXAP8 and RNF2, tumor stage I, without HBV infection and radical resection, were correlated with low-risk scores, and hence better patient survival." (PMID 32922554, 2020). "Altogether, our work supports that BMI1 and RNF2 bear a critical influence on the integrities of replication fork and CFSs, and emphasizes their tumor suppressive, rather than the often-perceived oncogenic, roles." (PMID 32142505, 2020). "Importantly, The knockdown of RNF2 expression through RNA interference significantly reduced the growth of xenograft tumors, whereas knocking down both RNF2 and SIK1 expression reversed tumor growth to the level of the control group." (PMID 27911266, 2017). "Conversely, HCC cells transfected with SIK1 expression vector partially reversed the oncogenic effect of RNF2 on tumor growth in vivo (data not shown)." (PMID 27911266, 2017). "It seems interesting that the prognostic value of the RNF2 expression was dependent not so much on the expression level found for individual cells but rather on the intratumoral expression by high fractions of the tumor cells." (PMID 29707138, 2018). "Interestingly, we found that the prognostic significance of RNF2 overexpression was more prominent in patients with either localized pathologic tumor stage or no nodal involvement." (PMID 26869491, 2016).
tumor (continued). "Because the expression of RNF2 in each of the normal bladder mucosa was negative or no more than 10% of the urothelium with positive staining, overexpression of RNF2 was scored only when more than 10% of the tumor cell nuclei were positively stained." (PMID 26869491, 2016). "Our data also suggest that Bmi1 levels, rather than RNF2 levels, may be better suited for assessment of gemcitabine efficacy in patients’ tumor specimens." (PMID 24614341, 2014). "Furthermore, it has been shown that PCA has significantly increased RNF2 expression and that RNF2 inhibition can increase TXNIP expression by binding to the TXNIP promoter, which may result in PCA cell-cycle arrest, enhancing apoptosis and preventing tumor progression." (PMID 36366411, 2022). "In addition, the survival of patients with different tumor differentiation statuses, TNM stages and Duke’s stages differed significantly between the RNF2-positive and RNF2-negative groups." (PMID 33346749, 2020).
infection (6 papers, 2012 to 2025). The state of being infected such as from the introduction of a foreign agent such as serum, vaccine, antigenic substance or organism. "In contrast, infection with RNF2-shRNA caused a significant decrease in RNF2 mRNA and protein levels, despite stimulation with EtOH." (PMID 40384855, 2025). "When wild-type Huh7OK1 cells were infected with HCV, the levels of H2Aub and RNF2 were reduced in a manner dependent on the number of days after infection in the presence but not in the absence of PA28γ." (PMID 39329491, 2024). "However, the mechanism by which the core protein induces the degradation of RNF2 after infection has not been elucidated." (PMID 39329491, 2024).
neurodevelopmental disorder (1 paper, 2025). A behavioral and cognitive disorder with onset during the developmental period that involves impaired or aberrant development of intellectual, motor, or social functions. "Our study provides mechanistic insight into how RNF2 missense variants contribute to neurodevelopmental disorders and implicates Polycomb dysregulation as a shared epigenetic mechanism in both developmental pathology and metastasis of carcinoma cells." (PMID 40831499, 2025).
RNF2 also shares sentences with these, for which no sentence is quoted: Ewing sarcoma (4 papers); leukemia (3); cardiac hypertrophy (2); osteosarcoma (2); pancreatic ductal adenocarcinoma (2); acute myeloid leukemia (1); adenocarcinoma (1); adenoma (1); AIDS (1); ameloblastoma (1); blood cancer (1); brain injury (1); breast (1); chronic myelogenous leukemia (1); cutaneous melanoma (1); Depression (1); ductal breast carcinoma (1); endometrial cancer (1); hemifacial microsomia (1); hypertrophic cardiomyopathy (1); invasive ductal breast carcinoma (1); kidney cancer (1); laryngeal carcinoma (1); liver cancer (1); lung squamous cell carcinoma (1); lymphoma (1); myelogenous leukaemia (1); neurological disorder (1); oculofaciocardiodental syndrome (1); odontogenic keratocysts (1).
A further 13 diseases each share a sentence with RNF2 in 1 paper.